APOA4 (apolipoprotein A4)
Diseases named in the same sentence as APOA4 in open-access papers (continued):
Sharing a sentence is not in itself a finding about the gene and the disease.
Insulin resistance (10 papers, 2017 to 2025). Increased resistance towards insulin, that is, diminished effectiveness of insulin in reducing blood glucose levels. "ApoA4 deficiency increases the hepatic lipid burden, insulin resistance, and metabolic inflammation." (PMID 36426356, 2022). "At one year, RYGB also produces larger triglyceride decreases, higher HDL-C and apolipoprotein A4, and improvements in hepatic insulin resistance versus diet alone, with parallel reductions in the need for antidiabetic, antihypertensive, and lipid-lowering medications." (PMID 41375653, 2025). "We speculate that APOA4 may be a physiologic compensation to insulin resistance that resolves after BS." (PMID 34441954, 2021).
Alzheimer disease (9 papers, 2016 to 2025). A progressive, neurodegenerative disease characterized by loss of function and death of nerve cells in several areas of the brain leading to loss of cognitive function such as memory and language. "APOA4 upregulation has been associated with PD, and C9 has been shown to be higher expressed in PD patients as compared to Alzheimer’s Disease patients." (PMID 34535682, 2021).
COVID-19 (9 papers, 2020 to 2024). A disease caused by infection with severe acute respiratory syndrome coronavirus 2. "The majority of the proteins associated with cholesterol metabolism, including APOC1, APOH, and APOE, were found to be decreased, except for APOA4, which was elevated in COVID-19 patients." (PMID 38672194, 2024). "The deficiency in apolipoproteins levels in COVID-19 compared to normal human plasma (NHP) and ICU-ARDS patients was most pronounced for APOA1, APOA2, APOA4, APOC3 and APOE." (PMID 37031181, 2023). "The apolipoproteins APOA1, APOA2 and APOA4 showed a 30% to 90% decline in COVID-19 and/or ICU-ARDS observation frequency compared to Normals (NHP)." (PMID 37031181, 2023). "We also observed that COVID-19 patients showed the down-regulation of apolipoprotein A-IV (APOA4) and apolipoprotein E in COVID-19 patients, possibly associated with macrophage function." (PMID 33203833, 2020). "Genetic and epigenetic mosaicisms of non-polymorphic Alus as well as polymorphic Alus located in other genes, particularly the apolipoprotein cluster (APOA1, APOC3, APOA4) and HLA loci, could also influence the host response and disease outcomes of COVID-19." (PMID 33390179, 2021). "Four of the five intestine-enriched proteins, i.e., ZG16, NLRP6, APOA4, and VIL1, showed decreased levels in serum of COVID-19 patients, whereas only CDHR2, a microvillar protein, showed elevated levels." (PMID 37739942, 2023). "Although the cholesterol metabolism pathway was significantly downregulated (including APOA2, APOC1, APOH, CETP, and APOA4), the increased levels of PCSK9 and APOB suggested the dysregulation of cholesterol metabolism in severe and critical COVID-19 patients." (PMID 35958562, 2022). "Among the significantly up- or down-regulated proteins in COVID-19 patient urine, metallothionein-1G, lipoprotein lipase, β2M, PRKACA, FOLR2, and APOA4, showed significant changes compared to both healthy controls and non-COVID-19 pneumonia cases." (PMID 33203833, 2020). "In particularwe observed a decrease in the HDL components APOA4 and APOC1 in both COVID-19 non-ICU and ICU/F patients (cluster 3) while APOA2, APOD, APOH, APOM and the HDL-associated PON1 protein appear to be decreased mainly in COVID-19 non-ICU patients (cluster 7)." (PMID 36348270, 2022).
liver fibrosis (8 papers, 2017 to 2025). "APOA4 is involved in several aspects of glucose homeostasis, including the promotion of glucose uptake in adipocytes, and is proposed to be an early diagnostic biomarker of prediabetes, impaired renal function, and liver fibrosis." (PMID 39339686, 2024). "In these regards, we suggested that the ApoA4 may reinforce TGF-β1-caused hepatic fibrosis due to the stimulation of HSCs." (PMID 29179490, 2017). "Remarkably, increased expression of APOA4 is considered an early marker for liver fibrosis in humans and has been observed in various models, including fibrosis in rhesus macaque or alcoholic hepatitis in human and mice models." (PMID 40819340, 2025). "Several NAFL patient cohorts have revealed the upregulation of APOA4 expression in the steatotic liver during the early stages of liver fibrosis and elevated plasma levels of APOA4 among NAFL patients." (PMID 36077090, 2022). "ApoA4 (encoded by ApoA4) has a variety of physiological functions, including anti-inflammatory and antioxidant activity, and circulating ApoA4 level has been used as a biomarker for the early diagnosis of liver fibrosis." (PMID 34604283, 2021). "With this integrated approach, the valuable role of the ApoA4 level was determined in predicting early hepatic fibrosis." (PMID 29179490, 2017). "Sensitivities and specificities of panel markers (ApoA4+HPG+ ApoA1) for early liver fibrosis detection can be greatly improved." (PMID 29179490, 2017). "Of note, apolipoprotein A4 in serum samples obtained from patients in the early stage of liver fibrosis were significantly increased compared to the healthy controls (p<0.001) while the area under curve was 0.966." (PMID 29179490, 2017). "Meanwhile, ApoA4 levels were significant in hepatic fibrosis patients versus the healthy controls (p<0.001)." (PMID 29179490, 2017). "Based on AUROC analysis, ApoA4 as an additional marker would increase the sensitivity and specificity in the detection and staging of liver fibrosis." (PMID 29179490, 2017). "Our results confirmed that ApoA4 was significantly upregulated in plasma samples obtained from subjects with mild liver fibrosis compared to those in the control group." (PMID 29179490, 2017). "Here, we preliminarily validated the relationship between plasma ApoA1, ApoA4, as well as haptoglobin and liver fibrosis to judge which plasma biomarker is better for the early detection of liver fibrosis." (PMID 29179490, 2017). "Taken together, we evaluated the levels of ApoA4 in the clinical plasma specimens which were obtained from healthy controls and patients with mild hepatic fibrosis." (PMID 29179490, 2017). "Together, these results suggest that microplastics may contribute to the development of liver fibrosis via oxidative stress-mediated mechanisms, while the observed APOA4 upregulation may serve as a potential early biomarker for this pathology." (PMID 40819340, 2025). "There is increasing evidence that oxidative stress may be an important modulator of liver fibrosis, and that apolipoprotein A4 (APOA4) and collagen IV could serve as biomarkers in this context." (PMID 40819340, 2025). "In this regard, overexpression of apolipoprotein A4 in early stage of liver fibrosis might magnify and imply the progression of hepatic fibrosis." (PMID 29179490, 2017). "We calculated the AUC value and showed that ApoA4 (area under curve: 0.966) and haptoglobin (area under curve: 0.887) might be the good biomarkers for the early identification of liver fibrosis." (PMID 29179490, 2017). "Therefore, ApoA4, along with additional biochemical parameters, could provide noninvasive assessment of early liver fibrosis, a possibility that warrants further experimental verification." (PMID 29179490, 2017).
liver fibrosis (continued). "Therefore, we will apply the animal model and intestine cells to further establish the novel contribution of ApoA4 to the liver injury in general as well as to explore molecular mechanisms whereby these cells increase their expression of extracellular matrix components during hepatic fibrosis." (PMID 29179490, 2017).
colitis (7 papers, 2020 to 2025). Inflammation of the colon. "Impact of HFD on DSS‐induced colitis may be linked to intestinal dysbiosis and specific genes such as Abca8b, Ace2, Apoa1, Apoa4, Apoc3, Aspa, Dpp4, Maob, Slc34a2, Slc7a9, and Trpm6." (PMID 39479684, 2024). "Overall, the findings indicate that the impact of HFD on DSS‐induced colitis may be linked to intestinal dysbiosis and specific genes such as Abca8b, Ace2, Apoa1, Apoa4, Apoc3, Aspa, Dpp4, Maob, Slc34a2, Slc7a9, and Trpm6." (PMID 39479684, 2024). "Independently, CCK and APOA4 each confer protection against inflammation and colitis through neural circuits that regulate energy homeostasis, reinforce epithelial barrier integrity, and suppress inflammatory signaling." (PMID 40723884, 2025). "APOA4 regulates lipid transport, increases energy expenditure, and exerts antioxidant and anti-inflammatory effects that alleviate experimental colitis." (PMID 40723884, 2025). "A recent study showed that APOA4 had an anti-inflammatory effect in alleviating dextran sulfate sodium-induced colitis in mice." (PMID 38044448, 2023). "Reduced APOA4 levels have been observed in the small intestine and plasma of patients with IBD, whereas acute administration of APOA4 alleviates inflammatory symptoms in animals with experimental colitis." (PMID 40723884, 2025).
hypertriglyceridemia (7 papers, 2011 to 2025). A laboratory test result indicating elevated triglyceride concentration in the blood. "Our NGS analysis revealed 10 rare variants at 4 genes (APOA1, APOA4, APOC2, and LMF1) related to hypertriglyceridemia." (PMID 35999587, 2022). "Patients with hypertriglyceridemia or cardiovascular disease have reduced plasma levels of APOA4." (PMID 37299447, 2023). "The ApoA1 and ApoA4 genes have the same transcriptional direction, while ApoC3 is transcribed in the opposite direction; moreover, its polymorphic variation can lead to hypertriglyceridemia." (PMID 32795354, 2020). "In addition, we analyzed the frequencies of 10 variant alleles in APOA1, APOA2, APOA4, and APOA5 that have been consistently linked to hypertriglyceridemia and elevated risks of CAD." (PMID 30076208, 2018). "We did not include ApoA4 SNPs in this study, because there is no ApoA4 SNP is associated with hypertriglyceridemia, except ApoA4 T347S associated with a TG-lowering effect." (PMID 21854571, 2011). "The lack of CYP7B1 decreases the postprandial hypertriglyceridemia response without inducing changes in APOA4 or total and HDL cholesterol." (PMID 41465421, 2025). "Further investigation regarding whether or not APOA4 infusion would downregulate hypertriglyceridemia through enhanced fatty acid uptake by adipose tissues and reduced lipids in lipoproteins in the circulation in lean and obese mice is needed." (PMID 37299447, 2023).
glaucoma (6 papers, 2016 to 2024). Increased pressure in the eyeball due to obstruction of the outflow of aqueous humor. "APOA1 and APOA4 were significantly 1.3 and 2.7 fold up-regulated in serum samples of glaucoma patients in comparison to controls." (PMID 34943212, 2021). "It should be noted that previous proteomic analysis in tears of glaucoma patients suggested variation in APOA4 levels, and recently this protein has been found as a constituent of the pseudoexfoliative material." (PMID 32585848, 2020). "They additionally performed an individual biomarker power discrimination with newly recruited glaucoma patients and found APOA4 yielded the best performance correctly discriminating 97% of glaucoma patients from healthy subjects with a sensitivity of 100% and a specificity of 95%." (PMID 34943212, 2021). "This represents APOA4 as a strong biomarker candidate to identify glaucoma patients in comparison to healthy subjects; however, it is not known whether it could distinguish other neurodegenerative diseases." (PMID 34943212, 2021). "Similarly, APOA4 levels significantly decreased in the glaucoma group DBA/2J_G at 14 months of age, when compared to pre-glaucomatous 4 month old mice (DBA/2J_G4 vs. DBA/2J_G14, 0.56-fold change)." (PMID 32585848, 2020). "Moreover, the five-protein panel consisting of complement C4a, complement factor H, ficolin-3, apolipoprotein A4, and transthyretin predicted the transition to glaucoma in 78% of cases, and to the advanced disease in 89%." (PMID 32585848, 2020). "Nevertheless, the significant deregulation of APOA4 during the development of glaucoma in mice may have unknown implications related with systemic alterations of immune response." (PMID 32585848, 2020). "Within the African American cohort, APOA1, APOA2, APOA4, and APOD levels were significantly higher among glaucoma patients." (PMID 34602085, 2021). "As a proof of concept, the use of a five-protein panel, consisting of C4a, CFH, FCN3, APOA4, and TTR predicts the transition to glaucoma disease in 78% of cases." (PMID 32585848, 2020). "Moreover, the five-protein panel, consisting of C4a, CFH, FCN3, APOA4, and TTR, predicted the transition to glaucoma in 78% of cases and correctly classified 89% of cases with advanced glaucoma in this animal model." (PMID 32585848, 2020). "GO analysis revealed a large impact of glaucoma on positive regulation of cholesterol esterification as evidenced by the upregulation of angiotensinogen (AGT), apolipoprotein C-I (APOC1), and apolipoprotein A-IV (APOA4)." (PMID 27788204, 2016).
hepatocellular carcinoma (6 papers, 2019 to 2025). A malignant tumor that arises from hepatocytes. "Simultaneously, CIDEC was found to be positively correlated with APOA4 in both normal liver tissues and hepatocellular carcinoma tissues." (PMID 36614113, 2022).
pancreatic cancer (6 papers, 2011 to 2024). "Another study showed that diabetic patients with pancreatic cancer had significantly lower plasma levels of APOA4 compared to cancer-free diabetic patients." (PMID 38067270, 2023). "APOA4 levels are also significantly decreased in patients with pancreatic cancer." (PMID 24708694, 2014). "Examples of consistent protein expression changes all the way up to clinical diagnosis of pancreatic cancer, were; gelsolin (GSN), apolipoprotein A4 (APOA4), coagulation factor 12 (F12) and lactotransferrin (LTF)." (PMID 24708694, 2014). "Further research is required to address these gaps, and to explore the relationship between carcinogenesis and APOA4 in non-diabetic pancreatic cancer patients." (PMID 38067270, 2023). "TCGA data suggested that APOA4 RNA expression was not significantly different among disease stages of pancreatic cancer; however, higher APOA4 level in tumor tissue appeared to have a less favorable outcome in patient survival." (PMID 32545216, 2020).
steatosis (6 papers, 2018 to 2024). Increased lipid within the cytoplasm of cells. "It was found that due to an increased expression of Apoa4, which in turn promoted the transport of celiac particles, and accelerated the secretion of triglycerides out of the liver, the symptoms of steatosis were reduced." (PMID 36010422, 2022). "Steatosis-induced Apoa4 expression leads to increased TG secretion and a reduction in hepatic lipid content by promoting VLDL particle expansion without increasing the number of VLDL particles." (PMID 29738435, 2018). "Hepatic Apoa4 expression is increased with high hepatic TG levels in steatosis and both acute and chronic hepatosteatosis." (PMID 29738435, 2018). "ApoA4 knockout rats and mice demonstrated significant hepatic steatosis." (PMID 38699158, 2024). "Besides, the mRNA and protein of APOA4 in the liver of mice with steatosis induced by high-fat diet was up-regulated by 43 times." (PMID 34708066, 2021). "Hepatic Apoa4 expression is strongly increased in the mouse models of steatosis." (PMID 29738435, 2018). "In mouse models, Apoa4 expression in the liver strongly increases during steatosis." (PMID 29738435, 2018). "We also looked at the mRNA expression of apolipoprotein A4 (APOA4) and perilipin 1 (PLIN1) because these lipid-related genes are consistently overexpressed whenever steatosis occurs, including in the context of NAFLD." (PMID 30147834, 2018). "Human genome-wide expression profiling studies have revealed that hepatic Apoa4 expression is also induced during steatosis, and that both alcoholic and nonalcoholic steatohepatitic CREBH induction increases hepatic Apoa4 expression." (PMID 29738435, 2018).
Hyperglycemia (5 papers, 2014 to 2022). An increased concentration of glucose in the blood. "Increased levels of ApoA4 are found in the serum from DM patients owing to its association with hyperglycaemia and high-density lipoprotein levels." (PMID 35432212, 2022).
leukemia (5 papers, 2013 to 2025). A malignant (clonal) hematologic disorder, involving hematopoietic stem cells and characterized by the presence of primitive or atypical myeloid or lymphoid cells in the bone marrow and the blood. "Proteins Clus, Ceru, ApoE, ApoA4, ApoA1, Gels, S10A9, Ambp, Actb, Cata and Afam have an important role in leukaemia prognosis, mainly as distinctive signals for aggressive leukaemia cases." (PMID 25537633, 2015).
lung carcinoma (5 papers, 2011 to 2023). "These contrasting findings around APOA2 and APOA4 within lung cancer subtypes are a testament to the molecular diversity of the disease." (PMID 38067270, 2023). "On the other hand, the role of APOA4 in lung cancer is contradictory depending on the lung cancer subtype." (PMID 38067270, 2023). "Interestingly, the APOA4 273–283 fragment demonstrated pathological stage-dependent up-regulation in lung cancer patients' sera, while the two-residue longer fragment APOA4 271–283 was significantly decreased in lung cancer samples." (PMID 21533267, 2011). "Given the value of sensitivity to detect lung cancer at an earlier stage, FIBA 6–15 (87.1%), APOA4 273–283 (61.3%), FIBA 5–16 (58.1%), and LBN 306–313 (58.1%) appeared to be the good biomarker candidates." (PMID 21533267, 2011). "Concerning the comparison between the normal group and the advanced-stage lung cancer group (stage-IIIb and IV), similarly 4 peptides (APOA4 268–284, APOA4 271–283, FIBA 5–15, and APOE 194–214) did not satisfy the criterion of p<0.05." (PMID 21533267, 2011). "Although ApoA4 has not been investigated in the context of smoke exposure, ApoA-I, another apopoliprotein, exhibits multiple protective features in normal and pathological lung conditions (asthma, emphysema, influenza, and lung cancer)." (PMID 31861112, 2019).